ALDH1B1 (aldehyde dehydrogenase 1 family member B1)
Diseases named in the same sentence as ALDH1B1 in open-access papers (continued):
Sharing a sentence is not in itself a finding about the gene and the disease.
tumor (continued). "To further confirm that ALDH1B1 contributes to tumor cell survival in the vasculature of distant organ, we implanted luciferase-expressing A549 cells with or without ALDH1B1 into female BALB/c athymic nude mice via tail vein injection." (PMID 41390768, 2025). "We depleted ALDH1B1 with short hairpin RNA (shRNA) in A549 cells, and found that ALDH1B1 depletion increased tumor cell death under confinement but did not significantly affect cell survival in unconfinement conditions." (PMID 41390768, 2025). "Significantly, both the knockdown of the ALDH1B1 gene through CRISPR, as well as the inhibition of its enzymatic activity resulted in attenuated colon spheroid and xenograft tumor growth, accompanied by the downregulation of colorectal CSC markers, such as the KRT15 and DCLK1." (PMID 36676146, 2023). "Interestingly, ALDH1B1 shRNA attenuated the ability of the U2OS cells to form tumors in xenograft experiments, illustrating its importance in the tumor-initiating process." (PMID 36676146, 2023). "As a control, the caspase-3 activity in tumor tissue was not changed by IKE in the absence or presence of EIF4E or ALDH1B1." (PMID 36274088, 2022). "Moreover, we implanted CSK23-depleted tumor cells with or without ALDH1B1 overexpression into randomized female BALB/c athymic nude mice via intracardiac injection." (PMID 41390768, 2025). "Similarly, both the proliferation and the survival of tumor cells were not influenced by ALDH1B1 depletion under no confinement." (PMID 41390768, 2025). "Instead, drug-induction suggested decrease for ITGB1/CD29c and ALDH1B1, while CD24, CD44, CD166, ALDH1A1 and Lgr5 were unchanged as detected by signals from microarrays with pooled tumor RNA from indomethacin-treated patients versus pooled tumor RNA from control patients." (PMID 25340937, 2014). "Similarly, overexpression of ALDH1B1 decreased lipid peroxidation levels and restored the survival and migration of CSK23-depleted cells in confining spaces, whereas CSK23 depletion showed no significant impact on lipid peroxidation or survival in unconfined tumor cells." (PMID 41390768, 2025). "Importantly, ALDH1B1 expression demonstrated a significant negative correlation with both 4-HNE accumulation and cell death in capillary-constrained tumor cells." (PMID 41390768, 2025). "However, tumor cells rescued with ALDHB1 ED could not recover the survival and the migratory capability of ALDH1B1-depleted cells in confinement." (PMID 41390768, 2025).
cardiovascular disease (2 papers, 2024). "The IREB2, MUT, ALDH1A2, and ALDH1B1 genes formed another cluster, with MUT, ALDH1A2, and ALDH1B1 showing associations with cardiovascular disease or infection." (PMID 39194753, 2024). "MUT, ALDH1A2, and ALDH1B1 are related to cardiovascular disease and metabolic pathways." (PMID 39194753, 2024). "Our primary focus is on their roles in cardiovascular diseases, the result uncovered involvement of ADK, BLVRA, ALDH1B1, UGDH, and HIBCH." (PMID 39369254, 2024).
colon polyps (1 paper, 2015). "In contrast, colon polyps from ApcMin mice showed very strong and universal ALDH1B1 expression in the epithelial cells." (PMID 25950950, 2015).
endocrine system disorder (1 paper, 2024). A disease involving the endocrine system. "For the CIDR+12 h top network, involved in Endocrine system disorders, Hereditary disorders and Organismal injury and abnormalities, NF-κB is linked to various hub genes, such as SUSD4, which negatively regulates complement activation, and ALDH1B1, which links to various aldehyde dehydrogenases." (PMID 38547106, 2024).
gastrointestinal disorders (1 paper, 2022). "In addition, four genes PDE4D, PKP2, NLGN1 and ALDH1B1 may be candidate genes for congenital heart defects or gastrointestinal disorders in OSH." (PMID 36302822, 2022).
metabolic disorders (1 paper, 2015). "In our study, ovarian HK1, HK2, PDHX and ACSS2 were repressed but FBP2 and ALDH1B1 were activated in DHT-treated rats, further complicating the metabolic disorders in those groups." (PMID 25887459, 2015).
ALDH1B1 also shares sentences with these, for which no sentence is quoted: adenocarcinoma (3 papers); colorectal adenoma (2); gastric cancer (2); infection (2); alcohol (1); alcoholic liver diseases (1); bladder cancer (1); colorectal tumors (1); COVID-19 (1); depression (1); fibrosis (1); gastric adenocarcinoma (1); gastric intestinal type adenocarcinoma (1); Glucose intolerance (1); hepatocellular carcinoma (1); Lynch syndrome (1); metastatic tumors (1); myeloma (1); nasopharyngeal carcinoma (1); non-alcoholic steatohepatitis (1); squamous cell carcinoma (1); thymoma (1); triple-negative breast carcinoma (1); uterine cancer (1); viral infection (1).